WASF3 (WASP family member 3)
Diseases named in the same sentence as WASF3 in open-access papers (continued):
Sharing a sentence is not in itself a finding about the gene and the disease.
tumor (continued). "The WASF3 protein expression profile in NSCLC was consistent with the mRNA expression result, which also correlated with the histological subtype and tumor stage." (PMID 25120680, 2014). "As anticipated, it was found that WASF3 expression in the NSCLC cases was significantly correlated with the histological subtype and tumor staging (P=0.001 and P=0.024, respectively), however, was not correlated with gender, age, differentiation status or lymph node metastasis." (PMID 25120680, 2014). "Thus, it appears that increased WASF3 expression could have a more general role in promoting metastasis in a variety of cancers that overexpress it, and so may be a valuable biomarker to predict tumor progression, as well as presenting a potential target, to prevent invasion and metastasis." (PMID 20717117, 2010). "RT–PCR analysis of cells re-cultured from these DU145/shWASF3 tumor xenografts, further confirmed the persistent knockdown of WASF3 expression levels (data not shown)." (PMID 20717117, 2010). "When injected subcutaneously into severe combined immunodeficiency (SCID) mice, tumor formation was significantly reduced for PC3 and DU145 cells with WASF3 knockdown and in vivo metastasis assays using tail vain injection showed a significant reduction for PC3 and DU145 cells." (PMID 20717117, 2010). "In addition, increased levels of E-cadherin were consistently seen in xenograft tumor tissues derived from SHOX2 knockdown cells compared with the knockdown control cells, which were dramatically suppressed in xenograft tumors when WASF3 expression levels were restored in SHOX2 knockdown cells." (PMID 34465361, 2021). "Furthermore, it was found that WASF3 may serve as a predictive marker of overall survival in NSCLC patients and may provide a potential target for anti-tumor therapy." (PMID 25120680, 2014).
WASF3 also shares sentences with these, for which no sentence is quoted: triple-negative breast carcinoma (5 papers); ductal carcinoma in situ (2); endometrial carcinoma (2); invasive breast carcinoma (2); adenocarcinoma (1); adenoma (1); breast carcinoma in situ (1); colorectal cancer (1); hepatocellular carcinoma (1); liver disease (1); lung adenocarcinoma (1); melanoma (1); metastatic disease (1); non-small cell lung carcinoma (1); osteosarcoma (1); ovarian tumors (1); sarcoma (1); stomach cancer (1).